ARL4C (ARF like GTPase 4C)
Diseases named in the same sentence as ARL4C in open-access papers (continued):
Sharing a sentence is not in itself a finding about the gene and the disease.
glioblastoma (8 papers, 2021 to 2025). The most malignant astrocytic tumor (WHO grade IV). "ADP‐ribosylation factor‐like‐4C (ARL4C) was highly expressed in PTEN‐deficient glioblastoma (GBM) cells and tissues with its capacity to boosted the proliferation of GBM cells." (PMID 33942991, 2021). "ARL4C plays an important role in tumorigenesis and also serves as a prognostic biomarker in glioblastoma, renal cell carcinoma, gastric, ovarian, lung and colorectal cancers." (PMID 38178862, 2023). "Previous studies found that high expression of ARL4C was found in low-grade glioblastoma (GBM) and was correlated with poorer progression-free survival (PFS) and overall survival (OS) in patients." (PMID 38178862, 2023). "Arl4c is reported to be involved mainly in tumor invasion and metastasis in glioblastoma, liver tumor, and ovarian cancer." (PMID 34849465, 2021). "Our investigation revealed that ARL4C is ubiquitously present in the plasma membrane and cytosol of U-251 (human glioblastoma cell lines), U-2 OS (human osteosarcoma cell line), and A431 (human skin cancer cell line), as evidenced by the HPA (Human Protein Atlas) datasets." (PMID 38178862, 2023). "ARL4C played an important role in glioblastoma and gastric cancer invasion and metastasis." (PMID 35607443, 2022). "Loss of phosphatase and tensin homolog deleted on chromosome 10 (PTEN) in primary human glioblastoma (GBM) stabilized ARL4C due to the AKT/mTOR pathway-mediated inhibition of ARL4C ubiquitination." (PMID 39767779, 2024). "Analyses of 325 patient specimens showed that ARL4C was highly expressed in glioblastoma (GBM) as compared with lower grade gliomas." (PMID 33403039, 2021). "By genetic inhibition experiments we validated that ARL4C is indeed highly and specifically essential for the growth of PFA cells, compared to ZFTA cells and glioblastoma cells." (PMID 37085539, 2023).
colon cancer (7 papers, 2016 to 2026). "In colon cancer-specific subgroup analyses, ARL4C consistently emerged as a risk factor for OS, PFS, and disease-specific survival (DSS)." (PMID 41328352, 2026). "Further analysis using the TNMplot and UALCAN databases confirmed elevated ARL4C expression in colon cancer tissues compared to adjacent tissues." (PMID 41328352, 2026). "Ursolic acid (UA) treatment significantly decreased the ARL4C protein level in human colon cancer and inhibited the AKT/mTOR signaling pathway." (PMID 39767779, 2024). "ARL4C promoted tumorigenesis in colon cancer, thereby representing a promising therapeutic target for curbing cancers." (PMID 35607443, 2022). "Our previous study demonstrated that ARL4C overexpression is detected in colon cancer and lung adenocarcinoma where genetic alterations in APC, β-catenin, and Ras are frequently observed." (PMID 27835592, 2016). "Since we already demonstrated that ARL4C is overexpressed in lung adenocarcinoma and colon cancer through aberrant activation of growth factor signaling and that ARL4C depletion suppressed cancer cell proliferation and migration." (PMID 27835592, 2016). "Additionally, another investigation highlighted that UA can impede the metastasis of colon cancer by enhancing the ubiquitination-mediated degradation of ADP-ribosylation factor-like GTPase 4C (ARL4C)." (PMID 41341590, 2025). "STC1 and ARL4C were found to be significantly upregulated in colon cancers." (PMID 35607443, 2022). "The relative expression of STC1 and ARL4C showed significant upregulation in colon tumor tissues." (PMID 35607443, 2022). "ARL4C expression was involved in migration and proliferation of HCT116 colon cancer and A549 lung adenocarcinoma cells." (PMID 27835592, 2016). "Since the activation of Wnt/β-catenin and EGF/Ras-MAPK signaling is not always clear in lung and tongue SCCs compared with colon cancers and lung adenocarcinomas, ARL4C might function as an oncogene in a certain types of cancers in which growth factor signaling is not constitutively activated." (PMID 27835592, 2016).
gastric cancer (7 papers, 2020 to 2024). A primary or metastatic malignant neoplasm involving the stomach. "ARL4C was identified as a peritoneal dissemination-associated gene and found to be highly expressed in gastric cancer cells." (PMID 32426352, 2020). "ADP-ribosylation factor 6 (ARF6) is downstream of ARL4C and has been reported to play an important role in promoting gastric cancer EMT." (PMID 37237373, 2023). "ARL4C is therefore proposed to be a novel biomarker and potential therapeutic target for ovarian and gastric cancer patients with peritoneal metastasis." (PMID 32780245, 2020). "Given its important role in cell detachment in ovarian and gastric cancer, investigation of ARL4C function in relation to PDA peritoneal metastasis is warranted." (PMID 32780245, 2020). "Silencing ARL4C markedly inhibited gastric cancer cell proliferation and metastasis." (PMID 37237373, 2023). "Indeed, ARL4C silencing impairs migration and invasion of gastric cancer cells in vitro." (PMID 32426352, 2020). "E-cadherin, HGF/c-MET, ARL4C, integrins and other ECM protein/cell receptor interactors, and EMT-related proteins all contribute to cell detachment process in ovarian and gastric cancers." (PMID 32780245, 2020). "Conversely, co-expression of ARL4C and TGF-β1 worsened the prognosis of gastric cancer patients." (PMID 37237373, 2023). "Moreover, the reduced expression of ARL4C leads to a decrease of the epithelial-mesenchymal transition (EMT) marker SLUG, as well as a reduction in lamellipodia and filopodia formation in gastric cancer cells." (PMID 32426352, 2020).
lung adenocarcinoma (6 papers, 2016 to 2025). A carcinoma that arises from the lung and is characterized by the presence of malignant glandular epithelial cells. "ARL4C expression is downregulated via the inhibition of the AKT pathway in lung adenocarcinoma A549 and 95-D cells, whereas exposure to benzo(a)pyrene (a carcinogen in smoke) increased ARL4C expression in human airway epithelial 16HBE cells via AKT activation." (PMID 39767779, 2024). "ARL4C was overexpressed in several cancer tissues with reported involvement in the initiation and progression of lung adenocarcinoma." (PMID 35607443, 2022). "The results are consistent with our recent observations that ARL4C is frequently expressed in atypical adenomatous hyperplasia, which is the possible precursor lesions and develops to lung adenocarcinoma." (PMID 34590580, 2021). "Lung adenocarcinoma patients from the TCGA dataset also showed high expression of ARL4C mRNA in tumor lesions with DNA hypomethylation in the 3’-UTR and inverse correlation between the levels of ARL4C DNA methylation and ARL4C mRNA expression." (PMID 27835592, 2016). "ARL4C was indeed highly expressed in tumor lesions of colon and lung adenocarcinomas, and ARL4C expression promoted migration, invasion, and proliferation of cancer cells both in vitro and in vivo." (PMID 27835592, 2016). "Taken together, these results suggest that ARL4C DNA hypomethylation of the 3’-UTR might be involved in the induction of ARL4C expression in lung adenocarcinomas." (PMID 27835592, 2016). "The relationship between ARL4C mRNA expression and ARL4C DNA methylation in the 3’-UTR or promoter region was also examined using lung adenocarcinoma cohorts from TCGA dataset." (PMID 27835592, 2016).
glioma (5 papers, 2021 to 2024). A benign or malignant brain and spinal cord tumor that arises from glial cells (astrocytes, oligodendrocytes, ependymal cells). "Therefore, higher ARL4C expression was associated with poorer prognosis in gliomas and ARL4C serves as a predictor." (PMID 33403039, 2021). "In addition, we analyzed the expression of ARL4C in clinical glioma specimens and its association with patient prognosis." (PMID 33403039, 2021). "Of interest also, TNFAIP6 was identified among ARL4C and MSN as a neural progenitor cell-associated chemoradiotherapy resistance gene set for the prognosis of glioma." (PMID 37511403, 2023). "We identified a high frequency of ARL4C alterations in sarcoma, brain lower grade glioma, and esophageal adenocarcinoma, emphasizing the critical role of mutations in the progression of tumorigenesis." (PMID 38178862, 2023). "Herein, we reported that ADP-Ribosylation Factor Like GTPase 4C (ARL4C) was highly expressed in glioma stem-like cells (GSLCs)." (PMID 33403039, 2021). "We also showed that ARL4C was associated with tumor grade and poorer OS of patients, suggesting that ARL4C acts as an oncoprotein in glioma." (PMID 33403039, 2021). "Validating the relationship between ARL4C expression and human glioma malignancy revealed that human gliomas expressed relatively higher levels of ARL4C than corresponding normal brain tissues." (PMID 33403039, 2021). "Analysis of the associative relationships ofindividual representatives of the selected pairs revealed that the level ofmRNAs encoded by the ELN, ARL4C,C9orf64, PLAT, and FKBP9genes associated with aggressive progression of glioma was increasedin the IDHwt group." (PMID 39539523, 2024). "In 325 patients with gliomas, ARL4C was markedly increased in high-grade tumors." (PMID 33403039, 2021). "In addition, higher level ARL4C expression in glioma was correlated with poorer progression-free survival and overall survival of patients." (PMID 33403039, 2021). "Overexpression of the genes whose transcripts act as potential targets fordysregulated miRNAs in the IDHmut and IDHwt groups is observed in moreaggressive glioma types: FKBP9 – CREB3L4, MCM4, MCM6, PSMB2, ARID1A, ARL4C, GRPEL2, and C9orf64." (PMID 39539523, 2024). "Here, we identified that ALDH1A3 as the main downstream target of ARL4C, and that ARL4C/ALDH1A3 axis was crucial for the tumorigenicity of glioma cells." (PMID 33403039, 2021).
ovarian carcinoma (5 papers, 2019 to 2024). A malignant neoplasm originating from the surface ovarian epithelium. "Recently, using immunohistochemistry, Arl4c was identified as a biomarker for a worse prognosis and a novel therapeutic target in endometriosis-associated ovarian cancer." (PMID 34849465, 2021). "Furthermore, upregulation of ARL4C was associated with a poor prognosis in endometriosis-associated ovarian cancer, Phosphatase and TENsin homolog deleted on chromosome 10 (PTEN)-deficient glioblastomas and renal cell carcinomas." (PMID 32426352, 2020). "It has also been demonstrated that the overexpression of ARL4C was detected in about 60% (25 out of 41) of OCCC cases, and that ARL4C predicted a poor prognosis in endometriosis-associated ovarian cancers, including OCCC." (PMID 31366141, 2019). "However, at the same time ARL4C also acts as a suppressor gene, inhibiting the progression of ovarian cancer, and, in addition, the overexpression of ARL4C enhances the sensitivity of the non-small cell lung cancer cells to the erlotinib." (PMID 39767779, 2024). "Concurrently, ARL4C in ovarian cancer may be classified as a tumor suppressor due to its high expression to impede cell migration." (PMID 38178862, 2023). "However, Arl4c was recognized as a tumor suppressor in ovarian cancer, as higher Arl4c expression inhibits cell migration and indicates a favorable prognosis." (PMID 34849465, 2021). "ARL4C was associated with reduced metastatic potential of ovarian cancer cells, in which it inhibits cell motility but not cell proliferation." (PMID 32426352, 2020). "Furthermore, ARL4C mRNA expression is lower in ovarian cancer samples of patients with a poor treatment response, while patients with higher ARL4C expression show increased overall survival." (PMID 32426352, 2020). "Based on the analysis of TCGA data, it was observed that ARL4C exhibited the highest expression levels in thymoma (THYM), cholangiocarcinoma (CHOL), and ovarian cancer (OV)." (PMID 38178862, 2023).
lung squamous cell carcinoma (4 papers, 2016 to 2023). "A recent study showed that deregulation of ARL4C was due to hypomethylation in its 3’‐UTR in lung squamous cell carcinoma." (PMID 33724652, 2021). "Conversely, high ARL4C expression only in THYM, OV, UCEC, and lung squamous cell carcinoma (LUSC) exhibited a negative association with the immune pathway." (PMID 38178862, 2023). "Moreover, a study recently found that upregulation of ARL4C, due to DNA hypomethylation induced by TET upregulation, promotes tumourigenesis of lung squamous cell carcinoma." (PMID 31352437, 2019).
colon adenocarcinoma (3 papers, 2022 to 2024). "In conjunction with RNA-seq and microarray data, ARL4C exhibited significantly elevated expression levels in the metastasis of esophageal carcinoma (ESCA), oral carcinoma, THCA, colon adenocarcinoma (COAD), kidney cancer, and pheochromocytoma and paraganglioma (PCPG) compared to primary tumors." (PMID 38178862, 2023).
endometrial cancer (3 papers, 2022 to 2024). Primary or metastatic malignant neoplasm involving the endometrium (mucous membrane that lines the endometrial cavity). "Aberrant expression or mutation of ARL4C may impact these biological processes, thereby being associated with the occurrence and development of diseases, such as endometrial cancer." (PMID 39268462, 2024). "In the case of the ADP-ribosylation factor (ARF)/ARF-like protein (ARL) family, it was observed that a high expression of ARL4D, ARL1, ARF1, and SAR1B in endometrial cancer is associated with better prognosis, while a high expression of ARL4C, ARL2, ARL10, ARL16, and ARL14 promotes worse survival." (PMID 35163161, 2022). "Recent studies show that expression of ARL4C induces proliferation in endometrial cancer cells; expression is significantly decreased after exposure to metformin (the most common anti-diabetic drug), leading to reduced proliferation." (PMID 36528638, 2022). "This is possible by regulating cell adhesion and the cell cycle; therefore, ARL4C is considered to be a promising target in the treatment of endometrial cancer." (PMID 35163161, 2022). "Human tissue microarrays were used to assess ARL4C protein levels in endometrial cancer." (PMID 35163161, 2022). "It has also been demonstrated that ARL4C belonging to the ARF/ARL family can induce the proliferation, migration, and invasion of endometrial cancer." (PMID 35163161, 2022).
hepatocellular carcinoma (3 papers, 2021 to 2024). A malignant tumor that arises from hepatocytes. "Serum level of Tbil is routinely used to assess liver function and studies have shown that ARL4C is highly expressed in primary hepatocellular carcinoma tumors and its expression is associated with poor prognosis." (PMID 33623009, 2021). "Similarly, ARL4C, abundant within neoplastic tissues, perpetrates its tumorigenic influence across various cancer forms including, but not limited to, colorectal, pulmonary, and hepatic carcinomas." (PMID 39624211, 2024).
renal carcinoma (3 papers, 2016 to 2025). A carcinoma arising from the epithelium of the renal parenchyma or the renal pelvis. "Parbivastat, through the inhibition of ARL4C, has been shown to significantly reduce proliferation, invasion, and migration in renal cancer cells." (PMID 40655141, 2025). "Knockdown of ARL4C inhibited the proliferation, colony formation, migration, and invasion of renal cancer cells." (PMID 35774359, 2022). "ARL4C acts as an oncogene in ccRCC, and its in-depth study can lead to the identification of new targets and prognostic markers for gene therapy of renal cancer." (PMID 35774359, 2022). "The differential expression of ARL4C in clinical renal cancer tissues versus adjacent normal tissues was further verified using immunohistochemistry and real-time quantitative reverse-transcription (qRT-PCR)." (PMID 35774359, 2022). "To further study the biological role of ARL4C in ccRCC, we used 786-O and ACHN cell lines for small interference transfection after screening and established two ARL4C knockdown renal cancer cell lines." (PMID 35774359, 2022). "In the present study, ARL4C expression was elevated in renal cancer, and proliferation, migration, and invasion of ccRCC cells could be inhibited by downregulation of ARL4C." (PMID 35774359, 2022). "Therefore, 786-O and ACHN cell lines were selected for small interference transfection, and then two types of ARL4C knockdown renal cancer cell lines were established." (PMID 35774359, 2022). "ARL4C acts as an oncogene in ccRCC, and an in-depth study of its mode of action may result in the identification of new targets and prognostic markers for gene therapy of renal cancer." (PMID 35774359, 2022). "To further verify that the Wnt/β-catenin signaling pathway regulates the protein expression of ARL4C in renal cancer cells, we cultured 786-O and ACHN cells with or without Wnt agonist 1 (Wnt agonist 1+/−) and ARL4C knockdown (si-ARL4C/si-NC)." (PMID 35774359, 2022).
renal cell carcinoma (3 papers, 2020 to 2023). "ARL4C is also suggested as a potential biomarker for poor prognosis in patients with renal cell carcinoma." (PMID 35607443, 2022).
ameloblastoma (2 papers, 2022 to 2024). The most common odontogenic tumor, arising from the epithelial component of the embryonic tooth and usually affecting the molar-ramus region of the mandible or maxilla. "For instance, ARL4C expression dependent on the RAF1-MEK/ERK pathway promotes ameloblastoma cell proliferation and osteoclast formation." (PMID 39268462, 2024).
atherosclerosis (2 papers, 2024 to 2025). A disease characterized by the build-up of fatty material and calcium deposition in the arterial wall resulting in partial or complete occlusion of the arterial lumen. "Knockdown of ARL4C also regulates genes that are involved in cholesterol metabolism and atherosclerosis with GO enrichment analysis, suggesting that ARL4C regulates atherosclerosis development." (PMID 40176913, 2025). "This review focused on the potential of ARL4C and its-mediated genes in atherosclerosis and agent development in the hope of providing knowledge for identifying drug development targets." (PMID 40176913, 2025). "ARL4C also plays a role in drug targeting; miR-26 promotes foam cell formation by reducing ABCA1 and ARL4C expression, supporting the development of drugs targeting atherosclerosis." (PMID 39268462, 2024). "Recently, ARL4C, a member of the ADP-ribosylation factor family of GTP-binding proteins, was found to promote cholesterol efflux to decrease foam cell formation, suggesting that ARL4C may be a new promising target for the treatment of atherosclerosis." (PMID 40176913, 2025). "Cell- or tissue-specific ARL4C localization may be an important inducer of its dual role in atherosclerosis." (PMID 40176913, 2025). "Thus, we focus on the role of ARL4C and its-mediated genes in atherosclerosis and agent development, which provide insights for the identification, research, and drug development of novel targets." (PMID 40176913, 2025). "Interestingly, ARL4C promoted the expression of LRP6, WNT5A, and WNT11, which suggests that ARL4C suppresses atherosclerosis development by enhancing LRP6 expression." (PMID 40176913, 2025). "Thus, we hypothesize that ARL4C may regulate atherosclerosis development by regulating these downstream genes." (PMID 40176913, 2025). "However, whether these genes are pro-atherosclerotic or anti-atherosclerotic depends on their location, suggesting that the role of ARL4C in atherosclerosis may depend on its location." (PMID 40176913, 2025). "Taken together, the downstream genes of ARL4C, including ABCA1, ALDH1A3, ARF6, ENHO, FLNA, LRP6, OSBPL5, Snail2, and SOX2 play an important role in atherosclerosis." (PMID 40176913, 2025). "Thus, ARL4C may promote atherosclerosis development by enhancing Snail2 expression." (PMID 40176913, 2025).